RN7SL230P (RNA, 7SL, cytoplasmic 230, pseudogene)
Gene: Miscellaneous RNA gene on chromosome 1 (179,900,262 to 179,900,564, forward strand). Ensembl gene ENSG00000264916.
Homologues: Orthologues: chimpanzee Metazoa_SRP (99% identical), macaque Metazoa_SRP (94% identical). Paralogues in human: RN7SL1 (88% identical), RN7SL3 (87% identical), RN7SL2 (87% identical), RN7SL45P (83% identical), RN7SL664P (83% identical), RN7SL566P (82% identical), RN7SL126P (82% identical), RN7SL7P (81% identical), Metazoa_SRP (81% identical), RN7SL14P (81% identical), RN7SL278P (81% identical), RN7SL296P (81% identical), and 701 more.